INS (insulin)
Diseases named in the same sentence as INS in open-access papers (continued):
Sharing a sentence is not in itself a finding about the gene and the disease.
Insulin resistance (continued). "Male hypogonadism is a disorder characterized by low levels of the hormone testosterone and patients may also have insulin sensitivity (IS) or insulin resistance (IR), such that they show different clinical complications and different metabolic pathways." (PMID 36361519, 2022). "Given that PE homeostasis is disrupted under HSD, which coincides with signs of insulin resistance in the fat body, we asked whether fat body-specific knockdown of Pect affects insulin sensitivity." (PMID 36201241, 2022). "Activation of inflammatory pathways may subsequently contribute to peripheral insulin resistance that is compensated for by higher insulin secretion." (PMID 36387874, 2022). "Also, both markers were found to be related with acanthosis nigricans, which is one of the clinical manifestations of insulin resistance, due to the presence of keratinocytes and fibroblasts able to respond to insulin through the expression of IGF1-R." (PMID 36213269, 2022). "Bears exhibit insulin resistance during hibernation and regain insulin sensitivity in the spring." (PMID 36185367, 2022). "This hypothesis provides an explanation for insulin resistance being driven by a dysregulation of lipid metabolism, and for observations that rigid membranes impair insulin signalling." (PMID 35169132, 2022). "Thus, this method represents another classification approach closely related to insulin resistance and insulin secretion as the pathophysiological hallmarks of type 2 diabetes." (PMID 34981134, 2022). "Recent studies showed that probiotics could effectively reduce insulin resistance and improve insulin sensitivity, which is an important strategy for improving MS." (PMID 36109620, 2022). "Parathyroid hormone (PTH) can mediate insulin resistance by inhibiting insulin signaling and reducing glucose uptake, while vitamin D could exert an insulin-improving effect by reducing PTH levels." (PMID 36313112, 2022). "Hypertriglyceridemia may contribute to an increased risk of T2DM by several possible mechanisms including impaired insulin sensitivity, decreased insulin secretion, impaired fatty acid oxidation, and muscle insulin resistance." (PMID 36438823, 2022). "The results showed that the IGTOGTT group had milder insulin resistance, relatively better early-phase insulin secretion, total insulin secretion, and compensatory ability of β-cells compared with those of the T2DMOGTT group even though HbA1c levels were both less than 6.5%." (PMID 36326358, 2022). "Insulin sensitivity correlates with plasma insulin clearance, presumably because both insulin action in and insulin clearance by tissues require insulin binding to its receptors and insulin receptor expression is downregulated in people with insulin resistance." (PMID 35054781, 2022). "Identification of potential mechanism(s) by which M. charantia improves insulin sensitivity and insulin signaling may supply new therapeutic targets for the treatment of obesity/dyslipidemia-induced insulin resistance." (PMID 35408574, 2022). "The low degree of insulin resistance in subjects with T2DM may enhance the influence of other factors that correlate with insulin sensitivity on SerpinB1 levels." (PMID 36331940, 2022). "Besides, the serum insulin and glucose levels were also measured followed by calculating the homeostatic model assessment of insulin resistance (HOMA-IR)." (PMID 36072413, 2022). "Increased IL-6 inhibits insulin signalling and leads to insulin resistance, mainly in the liver." (PMID 35711703, 2022). "MøFoxO1-KO mice also had significantly smaller adipocytes in visceral adipose tissues secondary to the improvement of insulin resistance in HFD-fed MøFoxO1-KO versus WT littermates, in keeping with the prevailing notion that smaller adipocytes are associated with enhanced insulin sensitivity." (PMID 35700043, 2022).
Insulin resistance (continued). "Besides, O. stamineus enhances insulin sensitivity and improves insulin resistance through other pathways, such as the PI3k/Akt signaling pathway, the AMPK pathway, and the JNK pathway." (PMID 35056765, 2022). "Our analyses showed that VAT ZAG expression levels were higher in patients with morbid obesity and low IR compared with those presenting high IR, and VAT ZAG expression levels were independently related to insulin, homeostatic model assessment of insulin resistance (HOMA-IR), and adiponectin." (PMID 35884810, 2022). "It is likely that the KO may improve the endocrine function of the pancreas by suppressing the altered insulin secretion for the elevated levels of glucose under insulin resistance." (PMID 36005486, 2022). "Fourth, current unavoidable glucocorticoid treatment, albeit relatively low dose, could affect insulin sensitivity and glucose metabolism, and at least in part leads to increased insulin resistance and impaired glucose tolerance." (PMID 35906625, 2022). "Homeostatic model assessment of insulin resistance (HOMA-IR) calculated by the concentration of plasma insulin and glucose is considered to be a reliable predictor for IR; whereas insulin is not a routine measurement in clinical practice and its determination has not been standardized." (PMID 36299856, 2022). "Obesity increases the risk of insulin resistance, a condition in which the body produces insulin but does not use it effectively, producing a reduced glucose uptake." (PMID 36364861, 2022). "However, LPCAT3 overexpression in skeletal muscle exacerbates glucose intolerance, and the inhibition of its expression enhances insulin signaling and improves insulin sensitivity, thereby improving insulin resistance." (PMID 35711841, 2022). "On univariate linear regression, insulin resistance (HOMA-IR) was associated with body mass index (BMI), waist circumference (WC), cohort with obesity, cohort consuming a high glycemic diet, hemoglobin A1c (HbA1c), and fasting insulin levels." (PMID 36570168, 2022). "CEACAM1, a transmembrane protein acting in hepatocytes to get rid of insulin excess hence limiting insulin resistance, has been shown to be lower in T1D and could be the link between NAFLD and T1D." (PMID 36531463, 2022). "Although the underlying molecular mechanisms of the relationship between a HFD and psychiatric symptoms are unclear, presumably the most likely major factor is insulin resistance, which may affect insulin-sensitive pathways and subsequently neuronal activity." (PMID 36345438, 2022). "The effects of LRYG on weight loss and insulin resistance improvement were not different between the two groups, and the difference in insulin secretory function was the most important factor associated with T2DM remission." (PMID 35831319, 2022). "Hypothalamic insulin resistance can result from insulin hypersecretion attributed to upregulation of parasympathetic activity, and previous study suggested that the severity of insulin resistance was apparently influenced by the degree of hypothalamic involvement, regardless of BMI." (PMID 36313753, 2022). "Increased insulin secretion reflects a compensatory mechanism for observed insulin resistance which may explain improved glucose tolerance in the offspring." (PMID 35869151, 2022). "Sortilin also appears to be a key factor in hepatic and muscular response to insulin, suggesting that it could be a link between insulin resistance and hypercholesterolemia." (PMID 35732620, 2022). "It was found to significantly reduce blood glucose, glycosylated hemoglobin, and glycosylated serum protein levels, increase the insulin sensitivity index, and decrease the IR index, Homeostatic Model Assessment for Insulin Resistance, effectively improving insulin sensitivity in diabetic rats." (PMID 36699072, 2022). "In type 1, there is a problem with insulin secretion, and in type 2–insulin resistance." (PMID 35757548, 2022).
Insulin resistance (continued). "suggest that in adults with T1D, insulin requirements during prednisone-induced insulin resistance may need to increase by 70% or more to normalize blood sugar levels." (PMID 36405706, 2022). "In addition, central insulin resistance is one of the new pathogeneses of T2DM, which is caused by the decrease of central insulin sensitivity 66,67." (PMID 35280695, 2022). "However, in type 2 diabetic patients, beta cells utilize excessive oxygen to match higher insulin demand and compensate for insulin resistance." (PMID 36139075, 2022). "The predominant ones are impaired glucose tolerance due to imbalanced insulin secretion and insulin resistance caused by a lack of peripheral glucose uptake." (PMID 36304231, 2022). "Insulin by its pleiotropic actions affects interorgan fluxes of almost all nutrient classes and in turn, insulin resistance results in impaired metabolite partitioning and that may therefore contribute to metabolic dysregulation." (PMID 35774538, 2022). "The pathogenesis of GDM is not completely understood; nevertheless, two factors could contribute to its development: β-cell dysfunction and failure in insulin secretion in response to insulin resistance induced by gestation." (PMID 35813659, 2022). "Extending the research to include the expression of other genes involved in the transmission of the insulin signal or regulating insulin sensitivity in adipocytes will allow a more accurate understanding of the mechanisms of reversing the existing insulin resistance by CM compounds." (PMID 35684107, 2022). "However, the subsequent study demonstrated that RGZ treatment decrease tissue TG content and improves insulin sensitivity in skeletal muscle while it aggravates fatty liver and insulin resistance in liver in A-ZIP/F-1 mice." (PMID 35013417, 2022). "NADP negatively correlates with insulin resistance indices, the glucose to insulin ratio (GLU:INS) and RQUICKI and positively with TBIL, GGT, ALB and LFI values in cows receiving niacin, while in the control group cows showed a negative correlation with GGT and a positive correlation with urea." (PMID 35739861, 2022). "During pregnancy, insulin resistance increases, and the same insulin concentration is higher." (PMID 35054078, 2022). "In conclusion, our results uncovered that statins inhibit GGPP production and induce insulin resistance in skeletal muscle cells through RhoA geranylgeranylation‐mediated insulin signalling‐dependent way and RAB8A geranylgeranylation‐mediated insulin signalling‐independent way." (PMID 35961942, 2022). "Type 2 diabetes is characterized by chronic hyperglycemia due to non-suppression of glucagon and reduced post-prandial insulin secretion, often worsened by obesity-associated insulin resistance." (PMID 35455439, 2022). "In addition, the ability of insulin to suppress Apo B secretion is impaired in obese patients and is marked by insulin resistance." (PMID 36145147, 2022). "Impaired tolerance of glucose and insulin is known to be a characteristic of insulin resistance." (PMID 36079819, 2022). "Also, we showed that hypercaloric diets promoted a state of metabolic deregulation, characterized by hyperglycemia, increased insulin secretion, insulin resistance, and glucose intolerance that is exacerbated by long-term intake." (PMID 35600301, 2022). "Insulin resistance (IR) is defined as the reduced responsiveness of target tissue to insulin." (PMID 36498726, 2022). "More specifically, it is speculated that NGAL could influence the fuction of beta cells and insulin sensitivity via iron metabolism, since elevated iron and ferritin concentrations can promote pancreatic injury and insulin resistance." (PMID 36145151, 2022). "Any abnormal change in pro-inflammatory cytokines (IL-6 and TNF-α) could diminish insulin sensitivity and contribute to insulin resistance." (PMID 36014565, 2022).
Insulin resistance (continued). "Reduced NO availability may be relevant not only to the development of atherosclerotic problems in T2DM but may also interfere with insulin-mediated postprandial glucose clearance and contribute to the development of insulin resistance." (PMID 35664415, 2022). "We explored whether low insulin clearance in Black African (BA) men could be explained by insulin resistance, subclinical inflammation or adiponectin concentrations." (PMID 34661756, 2022). "Furthermore, insulin resistance mediates the accumulation of intrahepatic fat through increased lipogenesis and lipolysis suppression, processes that further impair insulin signaling, increasing insulin resistance and thus promoting a vicious cycle." (PMID 36292115, 2022). "Therefore, another possible mechanism of HBP induced insulin resistance is that the increase of O-GlcNAcylation of insulin signal-related proteins antagonizes their phosphorylation." (PMID 35681484, 2022). "The underlying mechanism of anti-hyperglycemic activity of the compounds may be attributed by the inhibition of PTPase-1B, a major mediator of insulin signaling and insulin resistance." (PMID 35282429, 2022). "Including avocado in the diet regularly was hypothesized to improve insulin sensitivity in individuals with insulin resistance attributed to the bioactive components of avocado." (PMID 35700149, 2022). "Consequently, HM-chromanone treatment under insulin-stimulated conditions significantly restored the activation of the sub-kinases of IRS-1 in cells with insulin resistance." (PMID 36145191, 2022). "Furthermore, increased plasma levels of δVB and other betainized compounds as a consequence of a diet rich in whole grains were correlated with improved insulin resistance and insulin secretion." (PMID 36009329, 2022). "While physiologic levels of insulin and adiponectin activate endothelial nitric oxide synthase, that increases nitric oxide (NO), a regulator of vascular tone, insulin resistance and reduced adiponectin in the context of obesity diminish endothelial cell production of NO." (PMID 35391836, 2022). "Although there is no standard criteria for hyperinsulinemia, fasting insulin higher than 0.085 nM is considered to be associated with insulin resistance." (PMID 34921686, 2022). "Food intake with weak organic acids, including lactic acid, formic acid, pyruvic acid and acetic acid, could increase insulin sensitivity and improve insulin resistance in T2DM by lowering interstitial fluid pH values." (PMID 36112580, 2022). "Additionally, we examined association of sarcopenic obesity, defined as low D3Cr muscle mass and high percent body fat, with fasting plasma glucose, insulin, hemoglobin A1c and insulin resistance." (PMID 36490255, 2022). "α-MSH when present in the central nervous system can increase insulin sensitivity but may contribute to insulin resistance when circulate in the periphery." (PMID 35281489, 2022). "An elevated WHR indicates greater accumulation of visceral fat stores, a feature that negatively influences the metabolism of hormones such as insulin through free fatty acid secretion, which hinders insulin uptake by the liver leading to hyperinsulinemia and subsequent insulin resistance." (PMID 35621355, 2022). "Additionally, COS enhanced insulin signal transduction and glycogen synthesis while restricting gluconeogenesis in the liver and muscles, reducing insulin resistance (IR) as a result." (PMID 38647883, 2022). "Furthermore, the aberrant accumulation of triglycerides within the liver is promoted by hepatic insulin resistance, which is characterized by the failure of insulin to suppress glucose production and hepatic de novo fatty acid synthesis." (PMID 36101976, 2022). "Moreover, blood accumulation of BCAAs leads by itself to the development of further insulin resistance, whereas the decreased dietary consumption of BCAAs without calorie restriction enhances energy expenditure and improves insulin sensitivity in mice." (PMID 36235779, 2022).
Insulin resistance (continued). "Insulin levels may appear normal or elevated with normal β cell function, but their secretion is defective and insufficient to compensate for insulin resistance." (PMID 36438767, 2022). "Not only that, but TNF-α was also reported to modify the permeability of the intestinal capillaries, which could hamper the metabolic action of insulin, further aggravating insulin resistance." (PMID 35887957, 2022). "However, in intervention studies, a reduction of choline rather than TMAO showed significant associated with losses of body fat, fasting insulin and HOMA-IR, as well as 2-year improvements in glucose and insulin resistance." (PMID 35832425, 2022). "In addition, VAT %Tregs inversely correlated with both insulin resistance (p = 0.009) and plasma insulin levels (p = 0.007)." (PMID 36153324, 2022). "Chronic use of excessive insulin doses could lead to weight gain, resulting in increased insulin resistance and disturbances in triglyceride and cholesterol levels, and dyslipidemia." (PMID 34999914, 2022). "TZP may reduce the metabolic demand for insulin secretion from pancreatic β-cells by decreasing insulin resistance in patients with T2DM, and subsequently reducing sustained ß-cell stress." (PMID 36119737, 2022). "In addition, TMAO is positively associated with cardio-metabolic risk factors, such as insulin resistance and metabolic syndrome, and the SHR 1 g/L TMAO group showed dramatically elevated serum insulin levels in this study." (PMID 35975941, 2022). "As long as the patient is not susceptible to diabetic ketoacidosis, the recently introduced sodium-glucose co-transporter-2 (SGLT2) inhibitors may be used in patients both with insulin resistance and those with altered insulin secretion." (PMID 36422243, 2022). "Alternatively, a daily insulin dose above 200 units is considered severe insulin resistance." (PMID 36013252, 2022). "Moreover, in patients with insulin resistance, this diet improved insulin sensitivity according to the HOMA-IR (Homeostatic Model Assessment—Insulin Resistance) index." (PMID 36235635, 2022). "Insulin levels, insulin resistance (quantified by HOMA-IR), diastolic blood pressure, BMI, visceral adipose tissue (VAT), and waist circumference were significantly higher in the NAFLD subset compared to their counterparts (p < 0.01, p < 0.01, p = 0.05, p < 0.01, p < 0.01, p < 0.01, respectively)." (PMID 36159489, 2022). "The reason for the decrease in neurogenesis in MetS may be disruption of the insulin signaling pathway due to insulin resistance." (PMID 36474571, 2022). "Additionally, Metformin has a positive effect on markers of insulin resistance, such as fasting plasma glucose, fasting insulin levels, and homeostasis model assessment-estimated insulin resistance (HOMA-IR)." (PMID 36814831, 2022). "Additionally, the cord blood serum ANGPTL8 level was positively correlated with insulin and the homeostatic model assessment for insulin resistance." (PMID 35529083, 2022). "According to this paradigm, reduced hepatic insulin clearance preceded hepatic insulin resistance and steatosis that led to visceral obesity and insulin resistance in WAT, and eventually adipokine and NEFA release, to cause systemic insulin resistance." (PMID 36009446, 2022). "We reasoned that, as previously reported, the changes in insulin signaling may lead to insulin resistance in peripheral tissue." (PMID 36201241, 2022). "Our verified experiments in human L02 hepatocytes revealed that the expression levels of ADORA1 genes were upregulated in insulin resistance, while morusin treatment markedly increased cellular glucose consumption stimulated by insulin and downregulated ADORA1 expression." (PMID 36278175, 2022). "Consistent with these mechanistic underpinnings, studies of arsenic exposure with biochemical assessment of glucose homeostasis in non-pregnant adults have shown associations with greater insulin resistance and lower insulin secretion." (PMID 35031057, 2022).